EGFR (epidermal growth factor receptor)
Diseases named in the same sentence as EGFR in open-access papers (continued):
Sharing a sentence is not in itself a finding about the gene and the disease.
astrocytoma (continued). "EGFR Amp did not stratify overall survival (OS) in IDH-mutant diffuse gliomas and astrocytoma, while was significantly associated with poorer OS in IDH-wildtype diffuse gliomas, histologic grade 2 and 3 IDH-wildtype diffuse astrocytic gliomas and GBM." (PMID 38595969, 2024). "EGFR overexpression, indicating increased gene transcription independent of DNA alterations, ranges from 6% to 28%, from 27% to 70%, and from 22% to 89% in grade II, III, and IV astrocytomas, respectively." (PMID 39063215, 2024). "Second, the current cohort included IDH wild‐type histologically diagnosed GBMs but lacked IDH wild‐type astrocytomas that were positive for TERT promoter mutations, EGFR amplification, or + 7/−10 chromosome copy number changes." (PMID 37222229, 2023). "Similarly, in the context of the IDH mutant astrocytoma, the tumor with higher AUP1 was significantly correlated with PI3K-AKT-MTOR pathway (EGFR, PDGFRA, TSC2, MTOR), and autophagy signaling (ATG4B)." (PMID 37029364, 2023). "However, the mRNA overexpression frequencies of LANCL2 and EGFR in LGG samples were only around 10%, and little difference was shown in astrocytoma, oligoastrocytoma and oligodendroglioma." (PMID 34461927, 2021). "The survival analysis showed TERTp mutation as a prognostic factor for OS in the group of all IDH-wild-type astrocytomas and IDH-wild-type DAs, and the diagnosis of “astrocytoma, grade 4” with EGFR amplification was significant only in all IDH-wild-type astrocytomas." (PMID 34257410, 2021). "EGFR amplification was a significant factor for OS only in all astrocytomas (p = 0.0401), not in diffuse DAs (p = 0.7893) or AAs (p = 0.2877)." (PMID 34257410, 2021). "mGBM was defined as grade II-III IDH-wildtype astrocytoma without histological features of GBM but with one of the following molecular alterations: TERT mutation, EGFR amplification, or combination of whole chromosome 7 gain and whole chromosome 10 loss." (PMID 33235995, 2020). "1p19q loss and EGFR amplification which were mainly identified in oligodendrogliomas and primary GBM were not significantly different in different grades of astrocytoma." (PMID 25333259, 2014). "EGFR amplification occurs in 40 to 70% of primary GBMs, but is not observed in lower-grade astrocytomas." (PMID 21955618, 2011). "Overexpression of EGFR in astrocytomas can also occur without gene amplification, suggesting other mechanisms at transcriptional and translational levels." (PMID 20331873, 2010). "EGFR Amp seemed not to discriminate mOS in astrocytoma of different WHO grades, either." (PMID 38595969, 2024). "We observed that 2/60 (3%) IDHmut astrocytomas were reclassified as A4IDHmut due to CDKN2A/B homozygous deletion and 5/60 (8%) of IDHwt grades 2 and 3 were reclassified as GBMs (grade 4) due to one or more alterations in TERT, EGFR, and chromosomes 7 and 10, under the 2021 WHO criteria." (PMID 38672598, 2024). "Additionally, EGFR mRNA levels have been detected in less malignant astrocytomas and oligodendrogliomas, even in the absence of gene amplification." (PMID 39720087, 2024). "No studies were found specifically focused on EGFR-amplified IDH-mutant astrocytomas." (PMID 35669011, 2022). "In recombinant 1321N1 astrocytoma cells, P2Y2 agonist induces direct interaction of Src with the SH3 binding sites in the P2Y2 receptor to facilitate Src activation, which then recruits the EGFR into a protein complex with the P2Y2 receptor and allows Src to phosphorylate and activate the EGFR." (PMID 34064383, 2021).
astrocytoma (continued). "Similarly, of the six IDH-mutant astrocytomas that lived less than 12 months, none harbored + 7/ − 10 or EGFR amplification, and two had nearly zero copy number alterations." (PMID 34863298, 2021). "Interestingly, although in some cell types leptin signaling is dependent on EGFR transactivation, in 1321N1 astrocytoma cells the presence of the specific EGFR inhibitor, AG1478, does not abrogate the mitogenic effects induced by leptin alone." (PMID 28249041, 2017). "However, we did not identify an association between theses SNPs in EGFR and either OS and PFS in astrocytoma patients." (PMID 27437777, 2016). "Moreover, Notch1 and EGFR expression correlated in high-grade astrocytomas that were negative for the amplification of the EGFR gene." (PMID 25601901, 2014). "In our cohort of IDH-mutant diffuse glioma, EGFR Amp was found to co-occur with FGFR1, FGFR2, NTRK3 and RB1 alterations, which was not completely consistent in astrocytoma and oligodendroglioma." (PMID 38595969, 2024).
esophageal cancer (164 papers, 2006 to 2025). A primary or metastatic malignant neoplasm involving the esophagus. "It is important to emphasize that for EGFR-targeted therapy in esophageal cancer, two points must be considered: (i) EGFR-targeted therapy in esophageal cancer resistance due to EGFR-related gene mutations." (PMID 37598158, 2023). "The present results indicate that Fv-LDP-D3, and Fv-LDP-D3-AE exert prominent antitumor efficacy associated with targeting EGFR, suggesting their potential as promising candidates for targeted therapy against esophageal cancer." (PMID 35416106, 2022). "The epidermal growth factor (EGF) and its receptor (EGFR) gene-gene interactions were shown to increase the susceptibility to esophageal cancer." (PMID 36092955, 2022). "Mutations in RHBDF2 accelerate tumorigenesis by activating epidermal growth factor receptor (EGFR) signaling and are associated with tylosis esophageal cancer." (PMID 33796525, 2021). "Among the several antibodies used in the PIT for esophageal cancer, antibodies targeting EGFR, HER2 and cancer-associated fibroblasts (CAFs) have received much attention." (PMID 34834358, 2021). "KYSE520, an EGFR-amplified esophageal cancer cell line, showed loss of GAB1 Y659 phosphorylation with SHP099 treatment under conditions of EGF stimulation." (PMID 33755016, 2021). "Actually, gefitinib is a selective epidermal growth factor receptor tyrosine kinase inhibitor (EGFR-TKI), however its efficacy is limited to the esophageal cancer with EGFR gene-sensitive mutations." (PMID 31650447, 2020). "Overexpression of EGFR is seen in many solid tumors, including esophageal cancer, and is associated with poor prognosis." (PMID 31354907, 2019). "Loss of IGFBP3 also mediates acquired resistance to EGFR tyrosine kinase inhibitors, and upregulation of IGFBP3 is reportedly associated with increased chemosensitivity of esophageal cancer cells to nimotuzumab (anti-EGFR monoclonal antibody) with CDDP." (PMID 29849953, 2018). "In a subset of these cancers, most notably breast, colorectal, and esophageal cancers, increased EGFR expression is associated with advanced disease, tumor metastases, and poor prognosis." (PMID 27119071, 2016). "It has been shown that esophageal cancer with proof of EGF-R expression (epidermal growth factor receptor) is associated with a worse prognosis." (PMID 25907360, 2015). "We also found that the polymorphism in EGFR intron 1 was able to predict the prognosis of our patients with esophageal cancer after chemoradiation and surgery previously." (PMID 24945674, 2014). "The interaction of EGFR R497K with EGF at the +61A/G (rs4444903) polymorphism has been shown to enhance the risk of esophageal cancer." (PMID 24945674, 2014). "In a subset of these cancers, most notably breast, colorectal, and esophageal cancers, increased EGFR expression has been associated with advanced disease, tumor metastases, and poor prognosis." (PMID 24131756, 2013). "Multiple studies have shown that increased EGFR expression is associated with an overall decrease in survival in patients with esophageal cancer." (PMID 19636422, 2009). "In the present study, we found that EGFR is not only involved in the survival of esophageal cancer patients but is also associated with poor survival in association with FAP, which is a novel finding evaluating the association between EGFR signaling and the stroma in clinical specimens." (PMID 36418422, 2022). "In addition, the overexpression of EGFR was considered to be associated with prognosis in many cancers, including esophageal cancer." (PMID 34688250, 2021). "This indicates that ADAM17 and EGFR expression may increase the risk of esophageal cancer mortality." (PMID 25351873, 2015).
esophageal cancer (continued). "Given that predictive markers for other epithelial cancers such as mutations in KRAS, EGFR or BRAF are rarely detected in esophageal cancers, EGFR expression has been predominantly investigated for its potentiality of predicting treatment outcome for esophageal cancers." (PMID 26124180, 2015). "Over-expression of EGFR has been associated with poor prognosis of patients with esophageal cancer." (PMID 24945674, 2014). "Clinically, EGFR mutation and aberrant overexpression may lead to human carcinogenesis and tumor progression, including esophageal cancer." (PMID 24131756, 2013). "However, it remains unclear whether EGFR mutations in esophageal cancer predict benefits from treatment with EGFR inhibitors." (PMID 24103528, 2013). "Xin and coworkers provided evidence that more than 50% of EGFR-positive esophageal cancer (EsC) and PM cell lines were resistant to EGFR–tyrosine kinase inhibitors (TKIs)." (PMID 40149313, 2025). "For example, NAT10 enhances EGFR translation efficiency in esophageal cancer by enriching ac4C-modified tRNAs, thereby activating MAPK/ERK signaling." (PMID 40588654, 2025). "The overexpression of EGFR has been confirmed to be related to a variety of solid human tumors, including esophageal cancer." (PMID 40672372, 2025). "The combined depletion of NAT10 and treatment with the EGFR small-molecule inhibitor gefitinib synergistically inhibits esophageal cancer progression both in vitro and in vivo." (PMID 40881352, 2025). "TEAD induced the occurrence and drug resistance of esophageal cancer by directly attaching to the EGFR promoter to up-regulate EGFR expression." (PMID 39430767, 2024). "NAT10‐mediated ac4C acetylation of tRNA promotes EGFR translation and gefitinib resistance in esophageal cancer." (PMID 39640362, 2024). "GE11 peptide exhibits high affinity to epithelial growth factor receptors (EGFR), which are overexpressed in esophageal cancer at ∼13-fold higher compared to Barrett’s esophagus mucosa and ∼20-fold higher compared with normal esophageal mucosa." (PMID 37344759, 2023). "Our previous study also showed that icotinib combined with radiation therapy was safe and effective for older patients with esophageal cancer, particularly those with EGFR overexpression." (PMID 37251922, 2023). "Concurrently, EGFR overexpression has been observed in approximately 30-70% of esophageal cancers, and EGFR-TKIs have been demonstrated to disrupt cell proliferation and enhance the radiosensitivity of cancer cells." (PMID 37251922, 2023). "Cross-signaling between the ER and EGFR pathways has been observed in various tumor types, including esophageal cancer, indicating cooperative interactions between these receptors in tumor progression." (PMID 37370896, 2023). "A total of 132 cases of esophageal cancer were analyzed for epidermal growth factor receptor (EGFR), human epidermal growth factor 2 (HER2), and fibroblast activation protein (FAP) expression using immunohistochemistry." (PMID 36418422, 2022). "A study showed that 40–80% of esophageal cancer patients are diagnosed with high expression of EGFR, and erlotinib can be used as an adjuvant therapy for the treatment of esophageal cancer in combination with radiotherapy and chemotherapy." (PMID 35517789, 2022). "The high expression of EGFR is closely related to the proliferation, invasion and poor prognosis of esophageal cancer (EC) as well as the chemoradiotherapy tolerance in EC treatment." (PMID 36467103, 2022). "Esophageal cancer has been identified as a tumor with generally high expression of epidermal growth factor receptor (EGFR)." (PMID 36467103, 2022). "Summary of studies using anti-EGFR monoclonal antibodies with chemoradiation for resectable locally advanced esophageal cancer." (PMID 35912182, 2022). "The EGFR pathway has been involved in the pathogenesis and development of epithelioma, including esophageal cancer." (PMID 35898885, 2022).
esophageal cancer (continued). "Several studies reported high EGFR expression in most esophageal cancer patients (>70% in ESCC, 30–60% in EAC); therefore, EGFR-targeted NIR-PIT is ideally suited to treating esophageal cancer and human trials are underway." (PMID 35453596, 2022). "PTP1B promoted cell invasion by increasing EGFR protein expression through MYH9 in esophageal cancer cells." (PMID 36618415, 2022). "Our previous studies found that IGF-1R was also highly expressed in esophageal cancer, and the bispecific fusion protein targeting EGFR and IGF-1R that we constructed had very significant inhibitory activity against esophageal cancer in vitro and in vivo." (PMID 36142299, 2022). "Here, we examined the clinicopathological relationship between the ErbB tyrosine kinase receptor family and CAFs in clinical samples and demonstrated that both high FAP and EGFR expression strongly contributed to esophageal cancer prognosis." (PMID 36418422, 2022). "Recently, dexmedetomidine was reported to inhibit esophageal cancer progression via the miR-143-3P/epidermal growth factor receptor pathway substrate 8 in vivo." (PMID 34575688, 2021). "As such, we postulated that overexpression of EGFR observed in human esophageal cancer cells or tumor tissues is due to hyper-accessibility of chromatin structure near EGFR gene locus in cancer cells." (PMID 34722266, 2021). "In esophageal cancer cells exposed to a conventional chemotherapy regimen, an induction of PD-L1 was also observed that was prevented by blocking EGFR." (PMID 33951601, 2021). "Several clinical studies of first-generation EGFR tyrosine kinase inhibitors (TKIs) have been conducted in esophageal cancer." (PMID 34688250, 2021). "Several functionalized nanomedicines conjugated to PSs for esophageal cancer exist, with the most explored being the immunoconjugates using anti-EGFR and anti-HER-2 antibodies." (PMID 34834358, 2021). "The AuNPs was functionalized with anti-EGFR antibody and Anti-EGFR aptamer to detect esophageal cancer through the EGFR receptor selectively." (PMID 34834358, 2021). "The lncRNA LINC00152 had anti-tumor effects on esophageal cancer in the Eca 109 and Kyse 150 cells, the mechanisms were relative with EGFR pathway." (PMID 32190735, 2020). "Pingyangmycin can down-regulate the expression of EGFR in esophageal cancer cells and enhance the effect of cetuximab on xenograft of esophageal cancer in nude mice." (PMID 32068233, 2020). "EGFR, a transmembrane receptor kinase, is frequently overexpressed in various types of human cancers, including esophageal cancer." (PMID 32068233, 2020). "Phase 1 data for MRG003, a fully human anti-EGFR IgG1 antibody conjugated to monomethyl auristatin E stabilized disease in an EGFR-expressing esophageal cancer patient that remains on treatment at 12 weeks." (PMID 33364187, 2020). "Previous studies have shown that EGFR is highly expressed in esophageal cancer and promotes its progression." (PMID 32276266, 2020). "EGFR expression is observed in 50–70% of esophageal cancer patients and is correlated with inferior prognosis." (PMID 31258850, 2019). "Erlotinib and gefitinib, the small-molecule inhibitors targeting EGFR, have been evaluated in esophageal cancer in several clinical trials." (PMID 31781483, 2019). "The epidermal growth factor receptor (EGFR) signal pathway plays an important role in the carcinogenesis and progress of esophageal cancer." (PMID 31258850, 2019). "Next, we investigated the inhibitory effects of PT on the EGFR-expressing esophageal cancer cell lines." (PMID 30596104, 2018). "Further research about CET should pay more attention to these esophageal cancer patients with over-expressed EGFR." (PMID 30477458, 2018). "Epidermal growth factor receptor (EGFR), a transmembrane receptor kinase, is frequently overexpressed in various types of human cancers, including esophageal cancer." (PMID 30596104, 2018).